TTTY4 (testis expressed transcript, Y-linked 4)
Synonyms: TTY4; TTTY4A; LINC00123; NCRNA00123
Gene: Long non-coding RNA gene on chromosome Y (22,936,455 to 22,973,284, forward strand). Ensembl gene ENSG00000226906.
Homologues: Paralogues in human: TTTY4B (100% identical), TTTY4C (100% identical).